OR7E109P (olfactory receptor family 7 subfamily E member 109 pseudogene)
Synonyms: OST721; OR7E113P
Gene: Transcribed unprocessed pseudogene on chromosome 9 (90,742,526 to 90,743,380, reverse strand). Ensembl gene ENSG00000236316.
Diseases named in the same sentence as OR7E109P in open-access papers:
OR7E109P is named in the same sentence as 1 disease in open-access papers, as found by Europe PMC text mining. Sharing a sentence is not in itself a finding about the gene and the disease. The quoted sentences say what the papers report.
sarcopenia (1 paper, 2023). Progressive decline in muscle mass due to aging which results in decreased functional capacity of muscles. "Among deferentially expressed genes (DEGs) and the elastic net regression model, we found five common genes (TTC39DP, SLURP1, LCE1C, PTCD2P1, and OR7E109P) that discriminated between sarcopenia patients and healthy controls with a different range." (PMID 37138756, 2023).